AKNA (AT-hook transcription factor)
Description:
Centrosomal protein that plays a key role in cell delamination by regulating microtubule organization (By similarity). Required for the delamination and retention of neural stem cells from the subventricular zone during neurogenesis (By similarity). Also regulates the epithelial-to-mesenchymal transition in other epithelial cells (By similarity). Acts by increasing centrosomal microtubule nucleation and recruiting nucleation factors and minus-end stabilizers, thereby destabilizing microtubules at the adherens junctions and mediating constriction of the apical endfoot (By similarity). In addition, may also act as a transcription factor that specifically activates the expression of the CD40 receptor and its ligand CD40L/CD154, two cell surface molecules on lymphocytes that are critical for antigen-dependent-B-cell development. Binds to A/T-rich promoters. It is unclear how it can both act as a microtubule organizer and as a transcription factor; additional evidences are required to reconcile these two apparently contradictory functions (Probable).
Synonyms: KIAA1968
Tractability: PROTAC: ubiquitination databases record sites on it; its protein half-life has been measured.
Gene: Protein-coding gene on chromosome 9 (114,334,156 to 114,394,405, reverse strand). Ensembl gene ENSG00000106948.
Subcellular location: Cytoplasm, cytoskeleton, microtubule organizing center, centrosome, centriole; Nucleus
Subcellular location (Human Protein Atlas): Nucleoplasm; Centrosome; Cytosol; Nucleoli fibrillar center
Gene Ontology:
Molecular function: protein binding
Biological process: positive regulation of transcription by RNA polymerase II; delamination; epithelial to mesenchymal transition; neuroblast delamination; neuroblast division in subventricular zone; regulation of inflammatory response
Cellular component: centrosome; fibrillar center; membrane; nucleoplasm; nucleus; centriole; microtubule
Genetic constraint (gnomAD): Loss-of-function variants: 66 observed, 128.32 expected, observed/expected ratio (o/e) 0.51, 90% interval 0.42 to 0.63. The upper end of that interval is the gene's LOEUF score, 0.63, which puts it in group 2 of 6, group 1 being the genes least tolerant of losing a copy. Missense variants: 1,792 observed, 1,837.9 expected, observed/expected ratio (o/e) 0.98, 90% interval 0.94 to 1.01. Synonymous variants: 734 observed, 731.91 expected, observed/expected ratio (o/e) 1, 90% interval 0.94 to 1.07.
Homologues: Orthologues: chimpanzee AKNA (98% identical), macaque AKNA (94% identical), dog AKNA (70% identical), pig AKNA (66% identical), rabbit AKNA (66% identical), mouse Akna (58% identical), rat Akna (58% identical), guinea pig AKNA (57% identical), tropical clawed frog akna (27% identical). Paralogues in human: AKNAD1 (10% identical).
Diseases named in the same sentence as AKNA in open-access papers:
AKNA is named in the same sentence as 26 diseases in open-access papers, as found by Europe PMC text mining. Sharing a sentence is not in itself a finding about the gene and the disease. The quoted sentences say what the papers report.
cervical cancer (4 papers, 2019 to 2025). A primary or metastatic malignant neoplasm involving the cervix. "AKNA is an AT-hook transcription factor, with two AT-hook domains at the N- and C-termini: polymorphisms in one of them have been identified as risk factors for cervical cancer." (PMID 39201549, 2024). "In addition, the AKNA variant (−1372 C>A) is also a genetic susceptibility factor for cervical cancer in the Mexican population and knee osteoarthritis (KOA) in the Chinese and Mexican populations." (PMID 39996799, 2025). "Similarly, single nucleotide polymorphisms (SNPs) in the AT-binding region of AKNA are associated with a higher risk to develop cervical cancer, suggesting that impairing the function of AKNA favors the acquisition of a transformed phenotype." (PMID 34827707, 2021). "Furthermore, associations between AKNA gene variants with knee osteoarthritis and an elevated risk for cervical cancer due to a deregulation in the inflammasome network were reported." (PMID 31357536, 2019). "Previous studies have proven that one variant of the AKNA promoter, namely rs10817595 (−1372 C>A), is associated with Squamous Intraepithelial Lesion (SIL) and cervical cancer." (PMID 39996799, 2025). "In the context of cervical cancer, for instance, the E6 protein of high-risk human papillomavirus (HR-HPV) interacts with and downregulates both AKNA and its downstream target CD40, thus compromising immune surveillance." (PMID 39201549, 2024). "Notably, AKNA, acting as a tumour suppressor, serves as a prognostic indicator and influences susceptibility to various cancers, including acute lymphoblastic leukaemia, neck squamous cell carcinoma (HNSCC), cervical cancer (CC), and gastric cancer (GC)." (PMID 39201549, 2024).
gastric cancer (4 papers, 2020 to 2025). A primary or metastatic malignant neoplasm involving the stomach. "Here, we investigated the role of AKNA in gastric cancer (GC)." (PMID 32462010, 2020).
Intellectual disability (2 papers, 2021). "Using linkage analysis and whole-exome sequencing, we found a frameshift variant in exon 12 of AKNA (NM_030767.4: c.2737delG) that cosegregates with microcephaly, mild intellectual disability and speech impairment in a consanguineous family from Pakistan." (PMID 34680889, 2021). "Consistent with this new role of AKNA in neurogenesis favoring the delamination processes, a frameshift variant in exon 12 of akna was recently reported to co-segregate with microcephaly, a prenatal condition with varying degrees of intellectual disability." (PMID 34827707, 2021). "Here, we provide further evidence on its recently uncovered role in the regulation of neurogenesis by linking AKNA to MCPH in a consanguineous family from Pakistan with three affected children with consistently reduced head circumference and intellectual disability as the most prominent features." (PMID 34680889, 2021).
microcephaly (2 papers, 2021). A congenital or acquired developmental disorder in which the circumference of the head is smaller than normal for the person's age and sex. "In summary, we report on a novel primary microcephaly associated gene—AKNA—revealed by a homozygous truncating variant found in a consanguineous Pakistani family with three affected siblings." (PMID 34680889, 2021). "This suggests the possibility that the identified loss-of-function variant in our study could affect the timely expression of AKNA, thus disturbing the maintenance of the NPC pool and resulting in fewer neurons with thinning of the cerebral cortex and finally microcephaly." (PMID 34680889, 2021).
Vogt-Koyanagi-Harada Syndrome (2 papers, 2011 to 2019). "In human systemic autoimmune diseases such as Vogt-Koyanagi-Harada syndrome, AKNA was found to be downregulated in CD4+ T-lymphocytes." (PMID 31357536, 2019). "Our results showed a significantly decreased expression of CD18 and AKNA in CD4+ T cells from patients with active VKH syndrome." (PMID 21297967, 2011).
autism (1 paper, 2025). Persistent deficits in social interaction and communication and interaction as well as a markedly restricted repertoire of activity and interest as well as repetitive patterns of behavior. "The AKNA module, previously linked to autism, was downregulated and enriched for Ras-related GTPase and immune pathways, suggesting modulation of intracellular signaling and inflammation." (PMID 41367385, 2025).
Autoimmunity (1 paper, 2019). The occurrence of an immune reaction against the organism's own cells or tissues. "Similarly pertinent, because of their involvement in autoimmunity, are AKNA and MIB2 genes." (PMID 31511551, 2019).
cyst (1 paper, 2025). A sac-like closed membranous structure that may be empty or contain fluid or amorphous material. "The results showed a statistically significant difference in the relative expression of AKNA in ovarian cancer and cyst groups (p = 0.002)." (PMID 39996799, 2025).
epithelial ovarian cancer (1 paper, 2025). "In conclusion, the AA genotype of the AKNA variant (−1372 C>A) can cause a decrease in AKNA mRNA expression and AKNA protein expression in low-grade and high-grade ovarian cancer patients." (PMID 39996799, 2025). "This study is expected to serve comprehensive insights about the role of AKNA in pathogenesis and as a predictor of genetic susceptibility to epithelial ovarian cancer." (PMID 39996799, 2025). "AKNA gene variant (−1372 C>A) can cause a decrease in mRNA and protein levels in the low-grade and high-grade groups, so it has the potential as a genetic susceptibility factor in epithelial ovarian cancer." (PMID 39996799, 2025). "The reduced AKNA mRNA expression in the AA genotype may heighten inflammation, leading to excessive tissue repair during ovulation and a pro-carcinogenic tumor microenvironment that increases epithelial ovarian cancer risk." (PMID 39996799, 2025). "Based on this grouping, AKNA protein expression in CCC was higher than in other low-grade epithelial ovarian cancers." (PMID 39996799, 2025). "This overview will explore AKNA’s expression patterns, its relationship with immune mediators, and the implications for ovarian cancer progression." (PMID 39996799, 2025). "The AKNA protein expression in the low-grade and high-grade epithelial ovarian cancer groups was lower than that of cysts." (PMID 39996799, 2025). "Immunohistochemistry showed reduced AKNA protein expression in both low- and high-grade epithelial ovarian cancer, with lower intensity in low-grade cancer than in cysts and even lower in high-grade cancer." (PMID 39996799, 2025). "The aim of this study is to analyze AKNA gene variant (−1372 C>A) distribution and expression in normal and ovarian cancer in the Indonesian population." (PMID 39996799, 2025). "Given AKNA’s role as a centrosomal protein regulating microtubule stability, its low expression in ovarian cancer may lead to decreased E-cadherin and metastasis via uncontrolled EMT." (PMID 39996799, 2025). "The analysis of AKNA protein expression using immunohistochemistry showed a strong intensity of AKNA protein expression in cysts and decreased intensity in low-grade ovarian cancer and high-grade." (PMID 39996799, 2025). "AKNA is identified as a gene that regulates inflammation, immune response, and Epithelial–Mesenchymal Transition (EMT), which plays an important role in the progression of epithelial ovarian cancer." (PMID 39996799, 2025). "A significant negative correlation was found between the AKNA genotype rs10817595 (−1375 C>A) and the relative expression of AKNA mRNA in low-grade epithelial ovarian cancer (p = 0.037, r = −0.354) and high-grade epithelial ovarian cancer (p = 0.001, r = −0.572)." (PMID 39996799, 2025).
head and neck squamous cell carcinoma (1 paper, 2020). A squamous cell carcinoma that arises from any of the following anatomic sites: lip and oral cavity, nasal cavity, paranasal sinuses, pharynx, larynx, and salivary glands. "Moreover, by using weighted gene coexpression network analysis (WGCNA), AKNA was found to be a hub gene of head and neck squamous cell carcinoma (HNSCC) which is related to the immune response." (PMID 32462010, 2020).
Primary microcephaly (1 paper, 2021). Head circumference below 2 standard deviations below the mean for age and gender at birth. "It seems plausible that primary microcephaly in our family is the consequence of the lost C-terminus and impaired second PEST domain of the truncated AKNA protein." (PMID 34680889, 2021).
pulmonary disease (1 paper, 2021). "Although AKNA was first discovered as a maturation molecule of B lymphocytes, several studies revealed new functions for this protein in the immune system but also in pulmonary diseases, cancer, and neurogenesis, consistent with the fact that the lifespan of AKNA-KO mice is only a few days." (PMID 34827707, 2021).
Sepsis (1 paper, 2021). Sepsis is defined as life-threatening organ dysfunction caused by a dysregulated host response to infection. "Likewise, prediction models in cases of sepsis have proposed AKNA as a gene associated with immunosuppression and a high mortality rate." (PMID 34827707, 2021).
testicular germ cell tumor (1 paper, 2021). A germ cell tumor arising from the testis. "A study aiming to evaluate chromosomal and genetic alterations in cisplatin-sensitive and cisplatin-resistant human testicular germ cell tumors identified a downregulation of AKNA in the cisplatin-resistant tumors with chromosomal rearrangements in the 9q32-q33.1 region." (PMID 34827707, 2021).
viral infections (1 paper, 2012). "AKNA has not been previously reported to be differentially regulated during viral infections." (PMID 22590687, 2012).
cancer (6 papers, 2020 to 2025). A tumor composed of atypical neoplastic, often pleomorphic cells that invade other tissues. "AKNA variants in the promoter can affect the expression of AKNA, which is thought to have implications for the regulation in modulating the expression of genes related to inflammation, carcinogenesis, and cancer progression." (PMID 39996799, 2025). "The AKNA gene, encoding a transcription factor with an enigmatic role in cancer, adds complexity to our understanding." (PMID 38534332, 2024). "Furthermore, AKNA contributes to the de-regulation of the immune system in cancer, and it has been proposed as a susceptibility genetic factor and biomarker in CC, GC, and HNSCC." (PMID 34827707, 2021). "The decrease in AKNA protein expression is thought to be due to AKNA being activated to eliminate cancer pathogens, leading to increased inflammation in the cancer microenvironment, EMT imbalance, elevated MMP-9, and enhanced cancer colonization." (PMID 39996799, 2025). "Previous studies have revealed the crucial functions of AKNA in multiple physiological and pathological processes such as development, immune function, inflammation, and cancer." (PMID 32462010, 2020). "AKNA is encoded by a single gene located in the FRA9E region of chromosome 9q32, which is known to have the potential for mutations that cause inflammation and cancer." (PMID 39996799, 2025). "Increasing evidences indicated crucial function of AKNA might exert in multiple cancers." (PMID 32462010, 2020). "Additional cancer-relevant transcriptional regulators higher in responders before vaccination include SP2, NFYC, AKNA, MYPOP, and ZNF652." (PMID 39450169, 2024). "The AT-hook transcription factor, AKNA, is a nuclear protein that affects a few physiological and pathological processes including cancer." (PMID 32462010, 2020).
tumor (6 papers, 2020 to 2025). "AKNA regulates immune response gene expression and dampens inflammation, so loss of AKNA function may impair immune defense and facilitate tumor growth." (PMID 39996799, 2025). "AKNA transcription factor can enhance anti-tumor immunity by interacting with CD154 ligands and CD40 receptors." (PMID 39996799, 2025). "One of the genes that has a role in regulating inflammation, EMT, and anti-tumor immune response is the AKNA gene." (PMID 39996799, 2025). "Research indicates that AKNA expression varies across different tumor grades, suggesting its potential as a predictive biomarker." (PMID 39996799, 2025). "More interesting thing is that the expression level of AKNA was correlated with tumor location, metastasis, and TNM staging." (PMID 32462010, 2020). "It has been reported that in HNSCC, through WGCNA, AKNA was found to function as a hub gene that might involve in immune response, inflammatory response, and formation of the tumor microenvironment." (PMID 32462010, 2020). "AKNA is a potential tumor suppressor, and it might function in GC through affecting EMT-related pathways including chemokine signaling pathway, cytokine to cytokine receptor interaction, cell adhesion molecules, and jak-stat signaling pathway." (PMID 32462010, 2020). "In conclusion, AKNA could function as a tumor suppressor by modulating EMT-related pathways in GC." (PMID 32462010, 2020). "The most downregulated genes contained known tumor suppressors (ZNF831, AKNA, NR4A1, ARHGAP9, ZBTB16) and regulators of immune response (NLRC5, WDFY4, RASGRP2, IKZF1)." (PMID 39794830, 2025). "AKNA has been reported to regulate inflammation, immune response, and transition (EMT) in epithelial ovarian cancer, highlighting its multifaceted role in tumor progression." (PMID 41009979, 2025).
AKNA also shares sentences with these, for which no sentence is quoted: bladder cancer (2 papers); knee osteoarthritis (2); Primary Sjögren's Syndrome (2); autoimmune disease (1); coronary artery disease (1); myeloproliferative neoplasm (1); ovarian cancer (1); primary ciliary dyskinesia (1); progressive systemic sclerosis (1).